EGFR (epidermal growth factor receptor)
Diseases named in the same sentence as EGFR in open-access papers (continued):
Sharing a sentence is not in itself a finding about the gene and the disease.
rosacea (4 papers, 2014 to 2025). A chronic erythematous skin disorder that affects the face. "The pathophysiology of the rash associated with EGFR inhibitors is most reminiscent of acne rosacea (rosacea), for which a validated severity scale has already been developed." (PMID 24386952, 2014). "The changes induced by cathelicidins can further enhance vascularity in rosacea through the stimulation of downstream receptors, such as FPRL1 and EGFR, leading to additional increases in VEGF levels." (PMID 39918088, 2025). "Moreover, studies demonstrated the potential relationship between MLT target genes (MMP9, CCND1, EGFR, ICAM1, PTGS2, and SERPINE1) and rosacea-related key genes (IL-6, IL-1β, IFNγ, IL-17, and TNF-α)." (PMID 34899707, 2021).
SARS-CoV infection (4 papers, 2019 to 2022). "In the present study, a sum of three polymorphisms (SQSTM1 rs10277, IL1B rs1143627, EGFR rs712829) of 2-DG interacting genes may increase the susceptibility to SARS-CoV infections than other polymorphisms." (PMID 36164436, 2022). "Researchers explored the possibility of how SARS-CoV infection can influence EGFR signaling and consequently amplify the effect of the receptor’s activation." (PMID 34063231, 2021). "Dysfunctional EGFR signalling has been identified as a contributing factor to pulmonary fibrotic-like illness during SARS-CoV infections in animal models following the SARS-CoV pandemic in 2002, where authors speculated that inhibiting EGFR pathways would prevent fibrotic disease." (PMID 36203591, 2022).
sinonasal carcinomas (4 papers, 2021 to 2023). "The EGFR/MAPK/PI3K-mTOR-AKT and Wnt/β-catenin signaling pathways are implicated in some sinonasal carcinomas." (PMID 37888115, 2023). "Apart from MSI analysis, our targeted-NGS panel analysis of 136 sinonasal carcinoma and WES of the 10 patient-derived cell lines showed, as expected from previous studies, that EGFR exon 20 mutations (EGFRex20ins) are a hallmark of ISPs." (PMID 34885191, 2021). "Recently, identical mutations in exons 19 and 20 of the oncogene EGFR were reported in ISP and ISP-associated sinonasal carcinoma." (PMID 33048186, 2021).
soft tissue tumors (4 papers, 2017 to 2022). "Other sets contain a mixture of predictive and diagnostic biomarker considerations (e.g., to distinguish benign from malignant soft tissue tumors, or identify the presence of an EGFR activating mutation in a poorly differentiated tumor with equivocal immunophenotype)." (PMID 35852437, 2022). "To date, few studies have focused on the pathways of EGFR signaling in soft-tissue tumors." (PMID 29492209, 2018).
spinal cord injury (4 papers, 2012 to 2025). Penetrating and non-penetrating injuries to the spinal cord resulting from traumatic external forces (e.g., WOUNDS, GUNSHOT; WHIPLASH INJURIES; etc.). "Surprisingly, EGFR inhibitors can promote axon regeneration, reduce myelin loss, promote the upregulation of growth-related proteins, and ultimately improve the recovery of limb motor function after spinal cord injury." (PMID 38807603, 2024). "A convergence of evidence has indicated that inhibition of EGFR can be both neuroprotective and axon growth stimulatory by the modification of astrocyte-mediated inhibitory responses after spinal cord injuries." (PMID 22848811, 2012). "Furthermore, both AG1478 (an EGFR antagonist) and C225 (anti-EGFR monoclonal antibody) reportedly reduced the expression of phosphorylated EGFR (p-EGFR), enhanced axonal outgrowth and promoted functional recovery in rats subjected to spinal cord injury (SCI)." (PMID 40444141, 2025).
T-cell lymphoma (4 papers, 2020 to 2025). "Likewise, the EGFR-inhibitor gefitinib showed a markedly less pronounced antiproliferative efficacy in Jurkat cells, and no appreciable effect in the other three T-cell lymphoma cell lines, as compared with 3ClQuin-SAHA." (PMID 34445133, 2021). "Compared to T-cell lymphoma without PEH, skin T-cell lymphoma accompanied by PEH exhibited stronger expression of EGF and TGF-α on T cells and EGFR on epidermal cells." (PMID 40666517, 2025).
tauopathy (4 papers, 2019 to 2025). Neurodegenerative disorders involving deposition of abnormal tau protein isoforms (tau proteins) in neurons and glial cells in the brain. "Use of the NetDecoder informatics algorithm identifies key upstream biological targets, including MYC and EGFR, underlying the transcriptional and splicing changes in the protected compared to tauopathy mice." (PMID 31875547, 2019). "Future work will examine whether the interaction between Aβ and EGFR to alter tau hyperphosphorylation and whether ibrutinib regulates tauopathy in an EGFR-dependent manner in mouse models of AD." (PMID 40696386, 2025). "Future studies will compare the effects of EGFR inhibitors on tauopathy in young and aged mice." (PMID 36341365, 2022). "To address this hypothesis, we will verify the different roles of EGFR and EGFR inhibitors in the early and middle phases of gliosis and the mechanisms by which EGFR inhibitors modulate tauopathy in a later study." (PMID 36341365, 2022). "Therefore, the molecular mechanism by which ibrutinib's off‐targets (e.g., EGFR, JAK3, BMX) modulate tauopathy will be explored in a future study." (PMID 33709472, 2021).
Telangiectasia (4 papers, 2010 to 2021). Telangiectasias refer to small dilated blood vessels located near the surface of the skin or mucous membranes, measuring between 0.5 and 1 millimeter in diameter. "EGFR-agent-induced skin toxicities can be effectively treated at all stages and grade and are generally considered to be completely reversible except for telangiectasias." (PMID 23801914, 2013). "Because telangiectasias and hyperpigmentation usually occur as a result of photosensitivity, patients being treated with an EGFR inhibitor should be counseled to practice sun protection." (PMID 20680104, 2010).
thrombosis (4 papers, 2022 to 2025). "Increasing scrutiny has been applied to EGFR and PTEN in the induction of tissue factor (TF) with malignancy-associated thrombosis, leading our team to determine whether any correlations existed in our patient population between EGFR and VTE." (PMID 37232831, 2023). "EGFR non-amplified (wild-type) status was associated with an increased risk of thrombosis in patients >60 years old for this group of participants." (PMID 37232831, 2023). "Although EGFR is involved in angiogenesis and thrombosis, no significant risk factor has been determined between EGFR and VTE, except in patients older than 60 years of age, where we found that EGFR amplification had a protective effect on DVT risk." (PMID 37232831, 2023).
thymic epithelial tumors (4 papers, 2019 to 2023). "It has been pointed out that thymic epithelial tumors depend on tumor angiogenesis and growth signals from c‐KIT and EGFR for propagation." (PMID 37474689, 2023).
toxic epidermal necrolysis (4 papers, 2020 to 2023). Toxic epidermal necrolysis (TEN) is an acute and severe skin disease with clinical and histological features characterized by the destruction and detachment of the skin epithelium and mucous membranes. "Compared with EGFR-related skin ADRs as discussed in this article, the skin symptoms caused by drug hypersensitivity include maculopapular exanthema, Stevens Johnson syndrome, toxic epidermal necrolysis, etc.." (PMID 35505288, 2022).
urachal carcinoma (4 papers, 2016 to 2025). "Case reports have documented responses to targeted therapies in urachal carcinoma, including EGFR inhibitors (gefitinib, cetuximab), VEGFR inhibitors (sunitinib), and PARP/MEK inhibitors." (PMID 41333211, 2025). "Targeted EGFR inhibitors (e.g. gefitinib) have been used for urachal carcinoma recently." (PMID 29901861, 2018). "Meanwhile, the EGFR‐, PD‐L1‐, and MEK‐targeted therapies in the metastatic urachal carcinoma cases showed satisfactory response." (PMID 39462217, 2024).
Uterine leiomyoma (4 papers, 2013 to 2021). The presence of a leiomyoma of the uterus. "GPER and EGFR were highly expressed in human uterine leiomyoma compared to patient-matched myometrial tissues." (PMID 33818655, 2021). "Very recently it has been described that absence of tuberin leads to abundant nuclear localization of EGFR in rat uterine leiomyoma-derived and LAM patient-derived cells." (PMID 25699271, 2015). "A previous report demonstrated that telmisartan inhibited cell proliferation through EGFR followed by extracellular-regulated kinase (ERK) in uterine leiomyoma cells." (PMID 23451083, 2013). "Cadmium and proliferation in human uterine leiomyoma cells: evidence of a role for EGFR/MAPK pathways but not classical estrogen receptor pathways." (PMID 25343777, 2015).
-dependent (3 papers, 2015 to 2020). "Therapeutic agents that concurrently inhibit epidermal growth factor receptor and other angiokinases could be useful alternatives to combination therapies for epidermal growth factor receptor-dependent cancers." (PMID 26401847, 2015).
abdominal aortic aneurysm (3 papers, 2020 to 2022). Enlargement and ballooning of the vessel that supplies arterial blood to the abdomen, pelvis and legs. "Although erlotinib has recently been reported to protect against abdominal aortic aneurysm, the role of EGFR in IA formation remains arcane." (PMID 34729926, 2022). "Activation of EGFR has been reported to be involved in the formation of abdominal aortic aneurysms, and these can be prevented by inhibition of EGFR." (PMID 34729926, 2022).
adrenocortical tumors (3 papers, 2012 to 2016). "In this study, we have investigated EGFR protein expression, EGFR mutations, and EGFR gene copy number variations in adrenocortical neoplasms, specifically in 22 conventional ACC cases and 22 conventional ACA cases." (PMID 24457059, 2014). "However, there has been no comprehensive investigation of EGFR protein expression or somatic EGFR gene mutations and amplifications for adrenocortical neoplasms." (PMID 24457059, 2014). "In this study, we firstly evaluated the expression of IGF1R, EGFR and its signaling protein expression in human adrenocortical tumors, then investigated the crosstalk between EGFR and IGF1R pathway, and confirmed the therapeutic effect of co-inhibition of EGFR and IGF1R in ACC." (PMID 27105537, 2016). "Presence of EGFR in adrenocortical tumors has been demonstrated in the past." (PMID 23198184, 2012). "The expression of EGFR and IGF1R were evaluated in a series of adrenocortical tumors by immunohistochemistry." (PMID 27105537, 2016).
ampullary adenocarcinoma (3 papers, 2023 to 2025). "This pioneering study is the first to examine recurrence and survival outcomes in relation to druggable alterations (EGFR, HER2, and c-Met overexpression) among surgically resected ampullary adenocarcinoma patients at risk of recurrence, excluding very early-stage cases." (PMID 39123483, 2024). "Data with anti-EGFR–targeted therapies in ampullary adenocarcinomas are limited." (PMID 38136318, 2023). "Although the result showed the copy number of EGFR/ERBB2 showed a worse prognosis than the low copy number patients, the results showed no statistical significance between the copy number of EGFR/ERBB2 and the prognosis of ampullary adenocarcinoma." (PMID 39762212, 2025). "Besides, we checked the correlation between EGFR/ERBB2 amplification and the prognosis of ampullary adenocarcinoma." (PMID 39762212, 2025). "Given the limited role of anti-EGFR therapies in KRAS wild-type small bowel cancers or for right-sided colon cancers, anti-EGFR therapies for KRAS wild-type ampullary adenocarcinomas are not recommended." (PMID 38136318, 2023).
anaphylaxis (3 papers, 2019 to 2020). An acute hypersensitivity reaction that occurs from exposure to an allergen. "However, some episodes of anaphylaxis were observed in some patients with EGFR-positive tumours who received the anti-EGFR human/chimeric monoclonal IgG1 antibody cetuximab." (PMID 31544825, 2019).
anthracosis (3 papers, 2023 to 2025). A chronic lung disorder characterized by deposition of coal dust in the lung parenchyma leading to the formation of black nodules and emphysema. "Additionally, higher EGFR expression was observed in lungs presenting anthracosis, indicating a potential link between EGFR overexpression and air pollution-related carcinogenesis." (PMID 39902337, 2024).
arteriosclerosis (3 papers, 2018 to 2023). A vascular disorder characterized by thickening and hardening of the walls of the arteries. "As well as AhR, epidermal growth factor receptor (EGFR) activation by IS could also contribute to renal tissue remodeling and arteriosclerosis." (PMID 29772660, 2018).
autosomal dominant polycystic kidney disease (3 papers, 2015 to 2020). Autosomal dominant form of polycystic kidney disease. "Autosomal dominant polycystic kidney disease (ADPKD) is a genetic disease characterized by an overexpression of epidermal growth factor receptor (EGFR)." (PMID 33256255, 2020).
bacterial meningitis (3 papers, 2018 to 2023). Inflammation of the membranes surrounding the brain and spinal cord due to a bacterial infection. "Another evidence show that transactivation of EGFR may contribute to the development of bacterial meningitis-induced neuroinflammation." (PMID 33031061, 2020). "Ever rising levels of antibiotic-resistant bacteria and the emergence of their extended-spectrum antimicrobial-resistant counterparts remind us that EGFR could act as an alternative non-antibiotic target to better prevent and control bacterial meningitis." (PMID 30687645, 2018). "Transactivated EGFR recruitment of ACTN4, therefore, is likely to be a common mechanism utilized by multiple CNS-infecting bacterial pathogens for BBB penetration, and these molecules are potential targets for future prevention and therapy of bacterial meningitis." (PMID 30687645, 2018).
benign breast disease (3 papers, 2007 to 2015). "We used MCF10A cells, a spontaneously immortalized, non-malignant cell line obtained from a patient with fibrocystic disease, and stably infected them with EGFR-wild type (WT), EGFR-G719S (GS) or EGFR-DEL (E746-A750) (DEL) retroviral constructs." (PMID 25969993, 2015).
benign meningioma (3 papers, 2010 to 2021). A grade I, slowly growing meningioma. "EGFR expression is greatest in benign meningiomas and may serve a potential target for therapeutic intervention with selective EGFR inhibitors." (PMID 20509969, 2010).
bone sarcoma (3 papers, 2017 to 2023). A sarcoma that arises from the bone. "Furthermore, we discovered two GAs in the ALK and BRAF genes that occurred in bone sarcomas, while three GAs in the EGFR gene and one GA in the ERBB2 gene were only found in STS." (PMID 37546405, 2023). "Unfortunately, and despite international efforts, in bone sarcomas we could not identify any target such as KIT or EGFR through which to affect tumor biology in a significant way." (PMID 34831119, 2021).
Bowen disease (3 papers, 2009 to 2018). "The detection of EGFR-PPARGC1A by RT-PCR or variant assays may be useful for the diagnosis of such challenging cases or the evaluation of surgical margins, because the fusion can be detected at the in situ stage (actinic keratosis or Bowen’s disease)." (PMID 28978917, 2017). "Also EGFR expression in Bowen's disease resembled the expression pattern of CCHCR1." (PMID 19551138, 2009).
breast SCC (3 papers, 2021 to 2025). "It has been reported that p63, CK5/6, and EGFR are crucial immune markers for the diagnosis of primary squamous cell carcinoma of the breast (PSCCB)." (PMID 41026783, 2025). "A previous study reported that 87 % of breast SCC cases were EGFR-positive." (PMID 40896954, 2025).
cerebral small vessel disease (3 papers, 2021 to 2023). Cerebral small vessel disease is the term currently used to pathological processes that affect the brain parenchymal circulation (arterioles, capillaries, and veins). "For patients carrying variants outside EGFr region, no potential pathogenic mutation were identified in several other genes known to be common causal of cerebral small-vessel disease or vascular dementia (HTRA1, TREX1, COL4A1, COL4A2, GLA, APP, and ITM2B) by targeted next-generation sequencing." (PMID 34335700, 2021). "Thus EGFR may also be of value in the prediction of cerebral small vessel disease." (PMID 33478332, 2021).
chorioamnionitis (3 papers, 2014 to 2024). A morphologic finding indicating inflammation of the fetal sac membranes. "Further studies are needed to clarify the mechanisms how HDAC2 regulates the TGF-α/EGFR pathway in newborns suffering from maternal chorioamnionitis exposure." (PMID 24595367, 2014). "The additive effects of chorioamnionitis and mechanical ventilation are likely not due to changes in EGFR or ligands." (PMID 24788984, 2014).
choriocarcinoma (3 papers, 2017 to 2026). An aggressive malignant tumor arising from trophoblastic cells. "Similarly, in choriocarcinoma, a ternary nanocomplex composed of liposomes, polyinosinic–polycytidylic acid, and EGFR aptamer-conjugated DNA (EGFR-LPDS) was designed to deliver SATB1 siRNA." (PMID 41560835, 2026). "This study suggests that EGFR expression may be involved in the progression from “pre-invasive” lesions (IGCNU) to invasive lesions, because its expression is absent in the IGCNU tissue and is more frequent in choriocarcinoma, which represents a more aggressive phenotype of TGCTs." (PMID 28320414, 2017).
chronic asthma (3 papers, 2020 to 2025). An asthma that is characterized by the development of persistent airway inflammation and recurrent attacks of breathlessness and wheezing, which vary in severity and frequency. "Excessive EGFR activation may be involved with chronic airway inflammation, which causes chronic asthma." (PMID 33217964, 2020). "EGFR expression on airway epithelial cells also involves airway mucus production, which is a clinical feature of chronic asthma shown as airway hypermucus secretion by goblet cell hyperplasia." (PMID 33217964, 2020). "Pharmacological inhibition of EGFR signaling, using drugs such as AG-1478, gefitinib, or BIBX1522, has been demonstrated to reduce MCM in both acute and chronic asthma models, suggesting a contributory role of EGFR in MCM." (PMID 40406132, 2025).
Chronic colitis (3 papers, 2010 to 2022). A chronic inflammatory disease of the large intestine (colon, cecum and rectum). "Administration of recombinant IL-33 induced acute colitis but improved chronic colitis in a mice model via the mediation of amphiregulin/epidermal growth factor receptor (EGFR) signaling." (PMID 36614065, 2022). "A dissection of this mechanism reveals that TLR4 triggers elevated production of prostaglandin E2, increases Cox-2 induction, and influences epidermal growth factor receptor signaling (EGFR) in chronic colitis." (PMID 25076949, 2014). "It has been also demonstrated that TLR-4 signaling is crucial for colon carcinogenesis in chronic colitis, being responsible for induction of COX-2, increased prostaglandin E2 production, and activation of EGFR phosphorylation in chronic colitis." (PMID 21059221, 2010).